THBS1 (thrombospondin 1)
Diseases named in the same sentence as THBS1 in open-access papers (continued):
Sharing a sentence is not in itself a finding about the gene and the disease.
tumor (continued). "Conjointly, lumican impact on tumor response to matrix-targeted therapy was evaluated considering a previously validated peptide, namely TAX2, that targets matricellular thrombospondin-1." (PMID 28794454, 2017). "Osteopontin (OPN) and thrombospondin-1 (TSP-1) are extracellular matrix proteins secreted by stromal and tumor cells." (PMID 27422280, 2016). "Thrombospondin-1 (TSP-1) is a potent angiogenic inhibitor that is produced and secreted by many tumor types." (PMID 27756886, 2016). "THBS1 secreted by CD4+ and CD8+ T cells can negatively regulate angiogenesis in a tumour-bearing mice model." (PMID 25652121, 2015). "It is well established that the secretion of thrombospondin-1 (TSP-1) by activated stromal cells and its accumulation in the tumor microenvironment during dysplasia inhibits primary tumor growth through inhibition of angiogenesis." (PMID 26273699, 2014). "Since THBS1 hypermethylation is highly specific for CCSK, as we presented in this study, this finding should be useful for a molecular marker of this tumor." (PMID 23638012, 2013). "Met signaling has been shown to promote the remodeling of the tumor vasculature in breast and uterine tumors through the upregulation of VEGF and down regulation of thrombospondin-1 (TSP-1)." (PMID 22815748, 2012). "Several investigations have shown that EGR1 plays an important role in the control of tumor metastasis through regulation of cancer invasion-related genes, including TGF-β1, thrombospondin-1, and plasminogen activator inhibitor-1." (PMID 21283769, 2011). "Lipocalin inhibits ras-induced tumor angiogenesis through the down-regulation of VEGF expression and the up-regulation of THBS1 expression in tumor cells." (PMID 21853032, 2011). "Thrombospondin 1 (TSP1) has been shown to play a critical role in inhibiting angiogenesis, resulting in inhibition of tumor growth and metastases." (PMID 20976175, 2010). "Thrombospondin-1 (TSP-1) is involved in a variety of different cellular processes including cell adhesion, tumor progression, and angiogenesis." (PMID 20631908, 2010). "Thrombospondin 1 is a multifunctional extracellular matrix protein that functions as an angiogenic inhibitor and is involved in activating latent TGF-β secreted by tumor cells." (PMID 20515450, 2010). "THBS-1 is a well-known natural inhibitor of angiogenesis, and down-regulation of THBS-1 plays a critical role in the angiogenic switch in several tumor types." (PMID 20546602, 2010). "For instance, Thbs1, commonly overexpressed in the colonic stromal compartment, is thought to promote immunosuppression in CRC, while Spp1/Opn marks macrophages involved in tumor immune evasion." (PMID 40772227, 2025). "Also, we identified novel predicted tumor-suppressive ligands (SLIT3, DCN, CCN3, THBS1, INHA and INHBA), proteins (DNASE1L3, SULF1, PTEN, OAS1, and DAB2IP), and receptors (P2RX4, CDHR2, PTPRJ, and PTPRH) in MSC1 cells." (PMID 40564222, 2025). "In addition, THBS1/CD47 signaling also control tumor perfusion by indirectly regulating tumor blood flow, thereby limiting tumor growth." (PMID 40988744, 2025). "As THBS1 and BMPs are already known to promote tumor dormancy, we continued to investigate the role of PEAR1 and the chemokine CCL2 in endothelium-mediated induction of dormancy of various other tumor cell types." (PMID 41185039, 2025). "MSCs may up-regulate the anti-angiogenic molecules thrombospondin-1 (TSP-1) and endostatin, impairing neovascularization within the tumor microenvironment." (PMID 40643499, 2025). "Several studies have reported that THBS1 interaction with CD47 on NK cells and cytotoxic T cells inhibits their activation and limits granzyme B production that mediates antigen-dependent lysis of tumor cells." (PMID 41019041, 2025).
tumor (continued). "Since the communication between tumour cells and CAFs, unveiled by single‐cell transcriptomics, was mediated by MUC1 and FGF7/THBS1 to a certain degree, we examined the possibility of crosstalk between these two cell types in tumour tissues through expression information in spatial transcriptomics." (PMID 38778448, 2024). "Despite THBS1 and THBS2 possibly having variable effects on tumor cell adhesion and migration, in the TME, they often behave as adhesive and chemotactic proteins by binding several members of the integrin family through the TSR1s, TSR12s, TSR3s, and the N-terminal domains." (PMID 38339060, 2024). "Among these, CD273 and CD146 may indeed be MSC-specific, whereas CD36 (a receptor for thrombospondin-1), CD200 (also expressed on tumor cells), CD274 (PDL-1), and CD248 (endosialin) are also expressed in fibroblasts, often in a tumor context." (PMID 39201399, 2024). "Using THBS1 as a therapeutic target could enhance the efficacy of anticancer drugs, with studies showing that positive regulation of THBS1 leads to activation of the PI3K-Akt signaling pathway, promoting tumor growth and resistance to therapy." (PMID 39456895, 2024). "Most importantly, in mouse xenograft experiments with CCLP1, an established human cell line of iCCA, the simultaneous presence of blocking antibodies for THBS1, THBS2, and PEDF in the iCCA ECF was able to drastically reduce the tumor growth and the extent of tumor infiltration in local lymph nodes." (PMID 38339060, 2024). "Additionally, THBS1 modulates innate and adaptive immune cells through the CD47 signaling molecules, thereby restricting anti-tumor immunity." (PMID 39010084, 2024). "Interestingly, a novel thrombospondin 1 (THBS1) fusion with ALK (THBS1::ALK fusion) was identified through next-generation sequencing, providing new molecular insight into the pathogenesis of this rare tumor." (PMID 39171208, 2024). "THBS1 was deposited in the frontier of metastatic tumor cells, but this was not obvious in the primary tumors." (PMID 39304722, 2024). "Both treatments partially reduced primary tumor size with sustained reductions of liver and lymph node metastases in Thbs1-/- mice, but not in WT mice." (PMID 37749092, 2023). "Metastasis was strongly suppressed in Thbs1-/- mice, whereas the primary tumor was not affected despite increased cell death in these mice, prompting us to compare the immune TME at primary and metastatic sites." (PMID 37749092, 2023). "The RNAscope for THBS1 transcript and co-immunofluorescence of THBS1 with epithelial marker EPCAM confirmed the localization of THBS1 in the stroma, which was supported by transcriptomic analysis showing higher THBS1 expression in the tumor stroma." (PMID 37749092, 2023). "THBS1 is a TGF-β activator and has been found overexpressed in the tumor stroma." (PMID 36868311, 2023). "Using multiple immunofluorescence and immunohistochemistry, we then validated that THBS1 was primarily expressed in tumor stroma but not in tumor cells in the same sample." (PMID 37124494, 2023). "EPCAM-GFP+ BM-derived cells, that accounted for 21.2 ± 5.1% of the total cell population in tumors, had the highest expression of Thbs1 and Vcan compared to that in EPCAM+ tumor epithelium or EPCAM-GFP- residential stromal cells and also compared to that in MTO or MC38 cells." (PMID 37749092, 2023). "We observed that Thbs1 is exclusively expressed by tumour but not WT intestinal cells; surprisingly, we found that THBS1 is also essential for tumoroids’ growth." (PMID 35543624, 2022). "Given the role of THBS1 and SERPINE1 in tumor invasion and metastasis, it may explain the higher degree of malignancy in advanced SRC to some extent." (PMID 35372476, 2022). "Nevertheless, THBS1 levels did not increase further during therapy, independently of radiographic response, stable disease, or rapid tumor progression." (PMID 36362482, 2022).
tumor (continued). "Hypoxic exosomes was found to be enriched with proteins such as protein-lysine 6-oxidase (LOX), thrombospondin-1 (TSP1), and VEGF, and a disintegrin and metalloproteinase with thrombospondin motifs 1 (ADAMTS1), which are well-studied contributors to tumor progression, metastasis, and angiogenesis." (PMID 34444030, 2021). "In addition, platelets of tumor-bearing mice were observed to contain increased levels of thrombospondin-1 (TSP-1), which is highly correlated to tumor progression." (PMID 33634328, 2021). "Thrombospondin 1 (THBS1) (3.26-fold; p-value ≤ 0.05) which was significantly overexpressed in OKF6/TERT1-Shammah cells has been documented to be elevated in OSCC specimens induced by TGFBI which further promotes tumor migration and invasion." (PMID 33931671, 2021). "Cluster 0 (THBS1+MHClow TAMs) was prevalent in liver, with high expression of THBS1, MARCO and genes promoting the proliferation of EPCs and angiogenesis, such as EREG, AREG, and VEGFA, which could stimulate tumor growth and progression." (PMID 34489408, 2021). "To summarise, we were able to identify activation status-related proteins in fibroblast-derived EXOs by using mass spectrometry and validated three of the four selected candidate proteins (QSOX1, THBS1 and EDIL3) related to malignant transformation and tumour progression." (PMID 33802764, 2021). "FBN1, FN1, HGF, MMP9, THBS1, and VCAN may be new GC prognostic targets by affecting tumor purity, TMB, TME score, and multiple oncogenic signaling pathways." (PMID 33014013, 2020). "In addition to CORO1A, THBS1, PTP4A1, IL6, and CXCL16, the other nine genes were also upregulated in tumor tissues in TCGA." (PMID 32883954, 2020). "In contrast, during tumour progression, pro-angiogenic factors such as vascular endothelial growth factor (VEGF) and prostaglandins are highly expressed and anti-angiogenic factors such as thrombospondin-1 (TSP1) or endostatin are inhibited." (PMID 33321789, 2020). "We found the expression of THBS1 and MMP9 to be increased in LRIG2‐TG mice 48 h after TPA application, assuming that THBS1 expression could be involved in LRIG2‐mediated tumor initiation and progression." (PMID 31580518, 2019). "In addition, PMX/DCK-OP enhanced the release of an endogenous angiogenesis inhibitor, thrombospondin-1 (TSP-1), into both the blood circulation and the tumor microenvironment." (PMID 31337061, 2019). "Moreover, the tail metastasis proportion of the zebrafish group injected with tumor cells expressing a high level of TSP1 was significantly higher than that of other two groups (MDA-MB-231 and 231/sh-THBS1)." (PMID 31817450, 2019). "Furthermore, it was shown that THBS1 up‐regulates MMP9 expression in endothelial cells and promotes tumor cell invasion." (PMID 31580518, 2019). "Additionally, the tumor-immune biology of CD47 is complex and involves its other ligand thrombospondin-1 (TSP1)." (PMID 31276567, 2019). "We have further demonstrated that YAP/TEAD could increase THBS1 expression to promote FAK phosphorylation and FA formation, leading to the activation of tumour cell migration and invasiveness." (PMID 30055645, 2018). "Moreover, decorin restrains angiogenesis by binding to thrombospondin-1, TGFβ, VEGFR-2, and possibly IGF-IR, and then halting tumor growth by antagonizing oncogenic TKRs and angiogenesis." (PMID 28789706, 2017).
tumor (continued). "Stains for THBS1, JAG1, and EDN1 were available in the protein atlas database for the same tumor and showed significant expression of all three genes from our CINP transcriptional module in the VM tumor tissue but little stain in healthy tissues." (PMID 29162797, 2017). "Interestingly, in differentially expressed angiogenesis-related genes, thrombospondin-1 (TSP1), an anti-angiogenic gene, was higher expression in metastatic tumor cells than in primary tumor cells." (PMID 29100277, 2017). "In addition, the activation of the PI-3 and MAP kinase pathways also induces the expression of thrombospondin-1 and EMT-related genes to promote tumor invasion." (PMID 26859575, 2016). "In addition to blocking VEGFR2, YLL545 altered the expression of other molecules involved in tumor angiogenesis, including ITGAV, ENG, THBS1, FN1, and TEK." (PMID 27203384, 2016). "Furthermore, a large glycoprotein secreted by platelets in the blood, thrombospondin-1 (TPS-1), promotes tumor cell adhesion, migration, invasion, and angiogenesis, thereby potentiating tumor progression." (PMID 25742141, 2015). "To distinguish these tumors by the DNA methylation pattern more simply, we further selected four genes characteristically methylated among different tumor groups: ADRA1D, MGMT, VHL, and THBS1, and performed cluster analysis using the methylation average of 4 genes." (PMID 23638012, 2013). "Whereas, among many antiangiogenic factors, thrombospondin-1 (TSP-1) is a very potent angiogenesis inhibitor, and down-regulation of TSP-1 has been suggested to alter tumor growth by modulating angiogenesis in a variety of tumor types." (PMID 19250552, 2009). "Collectively, these observations highlight THBS1 as an example of CAF EV cargo that can differentially regulate angiogenic versus barrier phenotypes, underscoring the complexity of EV‐mediated remodelling in the tumour microenvironment and pre‐metastatic niche." (PMID 41179923, 2025). "Among these mediators, pigment epithelium-derived factor (PEDF), Thrombospondin 1 (THBS1) and 2 (THBS2) are highly expressed in iCCA tissue, where they act as inhibitors of angiogenesis and promoters of lymphangiogenesis, thereby facilitating tumor cells dissemination." (PMID 40001923, 2025). "However, the downregulation of key angiogenic inhibitors such as thrombospondin-1 (THBS1) and platelet factor 4 (PF4) suggests a disrupted regulatory balance that may promote unchecked neovascularization within the tumor microenvironment." (PMID 40710368, 2025). "Tumoural and CAF scores were first calculated for the union of tumour and CAF spots based on the expression signatures of the genes MUC1 and FGF7/THBS1, respectively (here, fibroblasts and CAFs were combined as overall CAFs since the former might transform into the latter in tumour conditions)." (PMID 38778448, 2024). "However, one of the most accepted consensuses includes doses ranging from one-tenth to one-third of the maximum tolerated dose and the sustained inhibition of tumor angiogenesis, which is detected as a minimal expression of VEGF and an increase in thrombospondin 1 (TSP-1)." (PMID 39201507, 2024). "Notably, selective upregulation of protein-lysine 6-oxidase (LOX-6), VEGF, thrombospondin-1 (TSP1) and other proteins has been observed, which converge in the tumor neovascularization region and may serve as key players in tumor angiogenesis." (PMID 37779868, 2023).
tumor (continued). "Additionally, thrombospondin 1 (THBS1), an oncogene in OSCC, is a tumor-specific ECM protein that is induced by TGFB1 and promotes cancer-cell migration while stimulating MMPs partly through integrin signaling expression, which facilitates the invasion of OSCC." (PMID 37686118, 2023). "IMT is the tumor that most frequently overexpresses ALK protein, however, in addition to no expression of skeletal muscle markers Myo-D1, Myogenin and Myogenin, genetically, IMT usually shows ALK re-arrangement with many other molecular partners including TPM3, KIF5B, CARS, and THBS1." (PMID 36998041, 2023). "In addition to an intrinsic role for TSP1 expressed by tumor cells, increased growth of B16 melanomas and F9 testicular teratocarcinomas was observed when implanted in syngeneic mouse strains lacking Thbs1." (PMID 33925464, 2021). "Among 54 GC patients with positive THBS1 methylation in PPLF samples, 72.2% (39/54) patients showed positive PPLF cytology, and 97.1% (33/34) patients with both positive cytology and THBS1 methylation in tumor tissues showed THBS1 methylation in paired PPLF samples." (PMID 34390026, 2021). "THBS1 is not a tumor suppressor gene, but the regulation of its expression in malignant cells by oncogenes and tumor suppressor genes mediates some of their effects on carcinogenesis, tumor progression, and metastasis." (PMID 33925464, 2021). "For example, CD47 could also interact with thrombospondin-1 (TSP-1), which is an extracellular ligand secreted by vascular and inflammatory cells; TSP-1 regulates cell motility, proliferation, and differentiation of some tumor cell lines in vitro." (PMID 34195295, 2021). "In addition, THBS1 was found to promote the proliferation of RAW264.7 cells and inhibit their apoptosis, as well as promote the proliferation, migration, growth, and survival of tumour cells in vivo." (PMID 33376743, 2020). "By employing a knockout mouse model, several studies have shown that the absence of THBS1 leads to increased vascularization and THBS1 protein inhibits tumor progression in several ways, including direct effects on cellular growth and apoptosis in the stromal compartment." (PMID 23638012, 2013). "Although thrombospondin 1 may be upregulated in malignant breast tissue, this is not sufficient for tumour growth and dissemination according to our results." (PMID 19396698, 2009). "Furthermore, inhibition of THBS-1 promoted angiogenesis and tumor growth of colon carcinoma xenografts, and the expression of THBS-2 in CRC is correlated with inhibition of angiogenesis and lower hepatic metastasis, highlighting the importance of ECM regulation to impair tumor progression." (PMID 35053521, 2022). "Furthermore, THBS1 showed higher expression in tumor tissues compared with normal tissues." (PMID 34635636, 2021). "Finally, THBS1 inhibition may be therapeutically important for reinforcing the efficacy of current anti-GBM treatments by not only acting at the vascular compartment, but also on invasive processes in the tumour periphery." (PMID 30850588, 2019). "PEDF is not expressed by the iCCA cells, whereas THBS1 and THBS2 are expressed and released in the iCCA TME by both tumor cells and CAFs." (PMID 40001923, 2025). "In particular, C3aR1, C5aR1, MMP-14, THBS1, and TREM2 were abnormally highly expressed in orthotopic tumor tissue but were not expressed in lymph node metastasis-negative tissues." (PMID 37744272, 2023). "In PTSMT, HGF, THBS1 and VEGFA are all expressed at low levels, indicating that HGF signalling does not contribute significantly to tumour angiogenesis." (PMID 24398114, 2014). "Thrombospondin-1 (TSP-1), mainly localised in fibroblasts of the CRC stroma, has been considered as an important negative-regulator of tumour angiogenesis." (PMID 21339979, 2010). "However, expression levels of FABP1, CD36, IRS1, THBS1, and TGFB1 did not significantly differ in various tumor stages." (PMID 36193307, 2022).